FAM90A11 (family with sequence similarity 90 member A11)
Synonyms: FAM90A11P
Gene: Protein-coding gene on chromosome 8 (8,012,342 to 8,015,352, reverse strand). Ensembl gene ENSG00000233115.
Subcellular location (Human Protein Atlas): Nucleoplasm; Nucleoli
Homologues: Orthologues: mouse Fam90a1b (28% identical), mouse Fam90a1a (27% identical), rat Fam90a1l1 (26% identical). Paralogues in human: FAM90A3 (99% identical), FAM90A5 (98% identical), FAM90A15 (98% identical), FAM90A13 (98% identical), FAM90A14 (98% identical), FAM90A16 (98% identical), FAM90A17 (98% identical), FAM90A9 (98% identical), FAM90A24 (97% identical), FAM90A18 (97% identical), FAM90A19 (97% identical), FAM90A23 (97% identical), and 9 more.